TNF (tumor necrosis factor)
Diseases named in the same sentence as TNF in open-access papers (continued):
Sharing a sentence is not in itself a finding about the gene and the disease.
Crohn disease (continued). "Additionally, concerning the findings that both MHC classes I and II contribute to the Crohn’s disease risk, the present study identified both antigen presentation mechanisms to be important in anti-TNF response." (PMID 36145641, 2022). "Moreover, polymorphisms of tumor necrosis factor (TNF) receptors which are linked to Crohn’s disease are associated with RA as well as poor response in some patients to ant-TNF treatment." (PMID 35655048, 2022). "Moreover, the production of tumor necrosis factor-α (TNF-α) was also reported to be associated with more intense inflammatory activity in patients with Crohn’s disease." (PMID 35422450, 2022). "For example, Crohn’s disease is an autoimmune inflammatory disease associated with a pathologic macrophage response that is treated by biologics such as tumor necrosis factor alpha (TNFα) inhibitors." (PMID 36013064, 2022). "The authors noticed that although several therapeutic options were considered including remdesivir, tocilizumab, or immune globulin, infliximab has been chosen because of the potential positive outcome of a TNF-α blockade in both Crohn’s disease and cytokine storm associated with PIMS-TS/MIS-C." (PMID 35628892, 2022). "In addition, certain clades of Ruminococcus gnavus have been associated with Crohn’s disease, whose inflammation is driven by TNF-α." (PMID 33765061, 2021). "This study suggests that anti-TNF therapy may be associated with reduced mortality compared with long-term corticosteroid use among veterans with Crohn disease." (PMID 33646314, 2021). "Taken together, our data suggest that FADS2 could have a pathogenic role, as TNFα is the most common treatment target in Crohn’s disease." (PMID 34229738, 2021). "In vitro studies have shown that TNF-α increases may also be associated with alterations in the regulation of the TJ proteins, for example claudin-2 in Crohn’s disease." (PMID 33172188, 2020). "Treatment with TNF-targeting drugs prevented the loss of vision due to uveitis in the majority of patients with Behcet’s disease and dramatically reduced the development of fistula formation in Crohn’s disease patients with inflammatory bowel disease." (PMID 32944095, 2020). "Anti-TNFα antibodies might also control muscle loss in chronic diseases such as Crohn's disease and rheumatic diseases." (PMID 33260150, 2020). "The damage that is caused by TNF to IECs is incompletely understood, but is of utmost importance, as it may play a role in Crohn's disease." (PMID 32914580, 2020). "Additionally, the reduced IL-10 sensitivity induced by ER stress particularly amplified the production of TNF and IL-23, two pro-inflammatory cytokines that have strong genetic associations with Crohn’s disease and are effective therapeutic targets in IBD." (PMID 31227842, 2019). "TNF-α −1031C allele had an association with Behcet’s disease, Crohn’s disease, and prostate cancer." (PMID 31652851, 2019). "Measuring the levels of TNF alpha inhibitors and associated antibodies in the blood could help clinicians to identify the best treatment strategy for a person with Crohn disease." (PMID 30341052, 2018). "IBD has been previously associated with increased levels of TNFα with upregulation of TNFα mRNA in colonic tissue in patients with Crohn's Disease and Ulcerative Colitis and many current therapeutic regimens involve a focus on blocking signaling through this molecule." (PMID 29876337, 2018). "However, the risk of MM was increased in patients with both Crohn’s disease and ulcerative colitis who had undergone treatment with anti-tumor necrosis factor-alpha (TNF-α) antibodies." (PMID 24188588, 2013). "Tight junctions between intestinal epithelial cells mediate the permeability of the intestinal barrier, and loss of intestinal barrier function mediated by TNF signaling is associated with the inflammatory pathophysiology observed in Crohn's disease and celiac disease." (PMID 22031828, 2011).
Crohn disease (continued). "Interestingly, Ruminococcus gnavus is associated with Crohn’s disease, likely through the ability of R. gnavus to synthesize and secrete glucorhamnan polysaccharides, which can lead to TNFα secretion by dendritic cells; it is also enriched in CRC patients compared to normal controls." (PMID 37190186, 2023). "Introduction of anti-tumor necrosis factor (anti-TNF) therapy for Crohn's disease stabilized ocular inflammation." (PMID 41778093, 2026). "Here, a TNF-overexpressing murine model (TnfΔARE/+) of Crohn's disease (CD) was used to investigate how pathobionts interact with host immune susceptibilities to drive region-specific disease." (PMID 41701533, 2026). "This is the first study, to our knowledge, to assess the cost-effectiveness of using anti-TNF medication from diagnosis and with continued maintenance therapy in adult patients with active Crohn’s disease." (PMID 41125135, 2025). "ART: assisted reproductive technology, CD: Crohn's disease, TNF-α: tumour necrosis factor-alpha, IPAA: ileal pouch-anal anastomosis." (PMID 40843056, 2025). "Anti-TNF-α therapies not only reduce inflammation but also help restore gut microbiota composition toward a healthier state in patients with Crohn’s disease." (PMID 40872514, 2025). "A large prospective cohort study of luminal Crohn’s disease demonstrated that only approximately one-third of patients maintained clinical remission after three years of anti-TNF therapy." (PMID 41199323, 2025). "The 2016 PANTS (Personalized Anti-TNF Therapy in Crohn’s disease) protocol, based on a three-year prospective study of over 1000 patients, established a strong link between HLA-DQA1*05 and anti-drug antibody development." (PMID 41153516, 2025). "Anti-tumor necrosis factor (TNF) treatment is recommended for perianal fistulas in patients with Crohn’s disease." (PMID 40495958, 2025). "The associated reduction in waist circumference implied the loss of central adiposity, which has been associated with intestinal inflammation through production of inflammatory cytokines such as TNF‐⍺ and IL‐6 from creeping fat seen in Crohn's disease." (PMID 39967287, 2025). "It is recommended for the induction of response and remission in patients with moderate-to-severe Crohn’s disease who have had an inadequate response to conventional therapy and/or to anti-TNF therapy." (PMID 40710828, 2025). "Kwak and colleagues performed single-cell network-based drug repositioning and identified vorinostat as a potential drug candidate for patients with anti-TNF-resistant Crohn’s disease." (PMID 40363705, 2025). "Such cytokine‐induced leakiness is prominent in Crohn's disease, where elevated TNF levels lead to high paracellular permeability and allow antigens/bacterial products to cross the gut lining, correlating with systemic immune activation." (PMID 40679787, 2025). "Claudin-5 redistribution was also found in colon biopsies of patients with Crohn’s disease or lymphocytic colitis and was mimicked by TNFα and IFNγ in colon epithelial cell lines in vitro." (PMID 40438590, 2025). "This process also promotes increased secretion of the proinflammatory tumor necrosis factor alpha (TNF-α), which plays a role in Crohn’s disease." (PMID 40809439, 2025). "All patients with Crohn’s disease were in clinical remission at the time of surgery and receiving maintenance anti-tumor necrosis factor (TNF) therapy." (PMID 41441911, 2025). "The sensitivity analyses are consistent and demonstrate robustness of the data supporting use of anti-TNF biosimilar medication for patients newly diagnosed with active Crohn’s disease." (PMID 41125135, 2025). "Infliximab (IFX), a monoclonal antibody targeting tumor necrosis factor-alpha (TNF-α), serves as a key biologic agent for inducing and maintaining remission in Crohn’s disease (CD)." (PMID 41438746, 2025).
Crohn disease (continued). "We conclude that, as with Crohn’s disease, an algorithm or a specific scoring system for ulcerative colitis is needed for the use of anti-TNF drugs as first-line treatment in pediatric ulcerative colitis." (PMID 41597331, 2025). "In recent years, monoclonal antibodies targeting TNF-alpha, such as infliximab, have been widely used to treat Crohn’s disease, demonstrating effectiveness in reducing inflammation." (PMID 40771912, 2025). "TNF inhibitors, biologic drugs targeting TNF-α, have revolutionized Crohn’s disease treatment by the significant reduction in inflammation and mucosal healing promotion, particularly in moderate to severe cases." (PMID 40283885, 2025). "Samples were selected from patients with IMID diagnosed with IBD (ulcerative colitis or Crohn’s disease) on maintenance treatment with anti-TNF or anti-IL-12/23 biologics." (PMID 40728886, 2025). "Refractory perianal fistulae in Crohn’s disease, which often survive multiple courses of anti-TNF therapy, have been closed durably by local implantation of allogeneic AASCs." (PMID 40650153, 2025). "In this study, cytokine analysis revealed significantly higher concentrations of IFN-γ and TNF-α in dogs with CE, consistent with previous findings suggesting a Th1-skewed response in canine CE and human Crohn’s disease (CD)." (PMID 40564263, 2025). "Fecal cytokine analysis has identified IL-2 and IFN-γ in norovirus-induced diarrhea and TNF-α in Crohn’s disease as potential biomarkers." (PMID 40458399, 2025). "For instance, during Crohn's disease or ulcerative colitis (UC), immune‐derived TNF‐α and interferon‐γ drive MLCK‐mediated myosin phosphorylation and occludin removal from TJs, compromising intestinal barrier function." (PMID 40679787, 2025). "“Top-down” treatment from diagnosis with anti-TNF results in lower healthcare resource use and better clinical outcomes in patients with Crohn’s disease compared to an “accelerated step-up” strategy." (PMID 41125135, 2025). "Established antibodies that target tumor necrosis factor α (TNF-α) as a contributing factor to Crohn’s disease include infliximab, adalimumab, and other monoclonal antibodies." (PMID 40363705, 2025). "TNF-α is a pivotal mediator of inflammation, and the monoclonal antibody infliximab, which targets TNF-α, is widely used to treat inflammatory diseases such as Crohn’s disease and ulcerative colitis." (PMID 40872514, 2025). "Promising results emerged from a phase 1b trial of CERC-002 in patients with moderate-to-severe Crohn’s disease who had previously failed anti-TNFα therapy." (PMID 41030453, 2025). "In patients with IBD, they are a cheap and effective treatment for ulcerative colitis (UC) and are used to prevent immunogenicity to anti‐TNF therapies in both UC and Crohn's disease." (PMID 40548539, 2025). "Guselkumab has also shown potential advantages over older biologicals like TNF inhibitors (e.g., infliximab, adalimumab) in Crohn’s disease." (PMID 40283885, 2025). "TNF inhibitors, specifically infliximab or adalimumab, had been used previously in 10.8% (4/37) of patients for conditions other than PG: Crohn's disease (infliximab, n = 2) and ulcerative colitis (infliximab, n = 1; adalimumab, n = 1)." (PMID 39535411, 2025). "Infliximab, a chimeric monoclonal antibody targeting TNF-α, is widely used in Crohn’s disease and other autoimmune conditions." (PMID 41287667, 2025). "In fact, therapies targeting TNF-α have been highly efficacious against intestinal chronic inflammatory diseases such as ulcerative colitis and Crohn’s disease." (PMID 39305371, 2025). "The development of neutralizing antibodies against TNF-α or IL-23 has introduced new treatment options for Crohn’s disease, similar to those in RA." (PMID 41002400, 2025). "This health economic analysis demonstrates that “top-down” treatment with anti-TNF therapy from time of diagnosis of Crohn’s disease results in lower overall healthcare costs compared to an “accelerated step-up” strategy." (PMID 41125135, 2025).
Crohn disease (continued). "The 2024 ECCO Guidelines on Therapeutics in Crohn’s Disease: Surgical Management advise against the cessation of anti-TNF agents, vedolizumab, and Ustekinumab, and that, as such, they should be continued until surgery." (PMID 40095509, 2025). "Recent advances in IL-23 inhibitors, including risankizumab, mirikizumab, and guselkumab, highlight their advantages over older treatments like TNF inhibitors for patients previously exposed to biological treatments or with refractory Crohn’s disease." (PMID 40283885, 2025). "Infliximab: This medication is a TNF-α inhibitor used to treat various autoimmune disorders, such as Crohn’s disease, which has been recently identified as a possible pharmacological risk factor for developing MRONJ." (PMID 40709114, 2025). "Infliximab, a chimeric monoclonal antibody directed against TNF-α, has been approved as a biologic agent for treatment of inflammatory and fistulizing Crohn’s disease." (PMID 40176789, 2025). "Despite this, receiver operating characteristic (ROC) curve analysis did not demonstrate a statistically significant predictive value of serum TNFα levels for distinguishing between remission and active disease in patients with Crohn’s disease." (PMID 41470167, 2025). "For patients with newly diagnosed Crohn’s disease, a “top-down” treatment strategy using anti-TNF biosimilar medication was less costly and more effective than an “accelerated step-up” strategy over a 5-year time horizon." (PMID 41125135, 2025). "The efficacy of anti-TNF therapy in Crohn’s disease, particularly when combined with an immunomodulator, has long been recognized and was reinforced in the PROFILE trial." (PMID 41125135, 2025). "Ruminococcus abundance increases in Crohn’s disease patients, and its metabolite glucorhamnan can induce dendritic cells to secrete the inflammatory cytokine TNF-α." (PMID 40076032, 2025). "Adalimumab, a TNF-α antagonist for Crohn's disease, also shows headache as a frequent ADR, though its benefits in maintaining remission often outweigh this risk." (PMID 41282415, 2025). "Crohn’s disease is treated with anti-inflammatory and immunosuppressive drugs, such as anti-TNF therapies, antibiotics, and surgery." (PMID 40553105, 2025). "Background and Objectives: Crohn’s Disease (CD) is a chronic inflammatory condition often treated with anti-TNF agents such as infliximab (IFX) and adalimumab (ADA)." (PMID 41470167, 2025). "Conclusively, mesalazine, azathioprine, steroids, and anti-TNF antibodies should be considered as first line therapy for metastatic Crohn ́s disease." (PMID 38762485, 2024). "We identified 67 IBD patients being treated with anti-TNF medications, 46 (69%) patients with Crohn’s disease and 21 (31%) with ulcerative colitis." (PMID 39525292, 2024). "TNF-α is also released and has been associated with an elevation in CD4+ and FoxP3+ regulatory T cells in the mucosa of Crohn’s disease patients." (PMID 37740772, 2024). "IFX was the first anti-tumour necrosis factor (anti-TNF) therapy approved for paediatric use in both Crohn’s disease (CD) and ulcerative colitis (UC)." (PMID 39771556, 2024). "The analysis demonstrated an increase in inflammatory response, IFNα response, IFNγ response, and TNFα signaling via NF‐κB in the colonic epithelium of both patients with ulcerative colitis and Crohn's disease compared to their normal counterparts." (PMID 39378064, 2024). "Anti-TNF use was the main cost driver, accounting for 64% and 31% of the total cost of treatments for Crohn’s Disease (CD) and Ulcerative Colitis (UC), respectively, in the Netherlands, in seven academic and seven general hospitals." (PMID 39458960, 2024). "In particular, CD4+ tissue-resident memory T (T_RM) cells have been found to be expanded in Crohn’s disease and are the major source of mucosal tumor necrosis factor α (TNFα), a principal mediator of intestinal injury." (PMID 38420127, 2024).
Crohn disease (continued). "The case discussed in this report represents a significant presentation of suspected MRONJ related to the long-term use of a TNF-α inhibitor for the treatment of Crohn's disease." (PMID 39045331, 2024). "In the context of Crohn’s disease, TNFα can show anti-inflammatory activity by down-regulating the CD40/CD40L pathway." (PMID 38256421, 2024). "Activation of the RhoA/ROCK pathway stimulates TNF-α and IL-1β production, with a positive correlation observed between RhoA and TNF-α in the inflammatory tissues of Crohn's disease patients." (PMID 38491049, 2024). "The PANTS (Personalised Anti-TNF Therapy in Crohn’s Disease) study, the largest prospective study of 955 luminal CD patients (≥6 years) treated with IFX, found that low IFX concentrations at week 14 were associated with non-response and ATI occurrence." (PMID 39771556, 2024). "A similar approach has been used to introduce large deletions in the porcine SRY gene for study causes of sex reversal in gene-edited pigs and a 93-bp deletion in the 3ʹ-untranslated region (UTR) of the TNFα gene to generate a porcine Crohn’s disease model." (PMID 39684387, 2024). "The efficacy of anti-TNF therapy in Crohn’s disease (CD), such as infliximab, is often compromised by the development of anti-drug antibodies (ADAs)." (PMID 39055374, 2024). "Reports suggest that UST is more effective than VDZ for treatment retention and steroid-free remission rates in patients who previously failed anti-TNFα antibody therapies, although this was reported in Crohn’s disease." (PMID 39425179, 2024). "Based on these preclinical studies, a pilot intervention study has been undertaken including a daily supplementation of purple corn extract (RED) to Crohn’s disease patients under Infliximab therapy, a monoclonal antibody against TNF-α." (PMID 38999902, 2024). "This family is closely related to inflammation, particularly increased TNF‐α levels, Crohn's disease, and colorectal cancer." (PMID 39620016, 2024). "Ustekinumab in the long-term is an effective, sustainable, and safe therapeutic option for Crohn’s disease patients with severe disease phenotype and high previous anti-TNF biological failure, requiring frequent dose intensifications." (PMID 38942890, 2024). "Anti-tumor necrosis factor alpha (TNFα) therapies have revolutionized the management of Crohn’s disease (CD)." (PMID 39677079, 2024). "The PANTS study recruited patients from across the UK, and we believe our findings will be generalisable to patients with Crohn’s disease treated with an anti-TNF across other western populations." (PMID 37551994, 2024). "S100A12 also exists in a dimer or hexamer form, and Ca2+-bound forms of S100A12 are reported to bind directly to soluble tumor necrosis factor (TNF) and affect the efficacy of anti-TNF therapy in patients with juvenile idiopathic arthritis and Crohn’s disease." (PMID 38256103, 2024). "The Step-Up/Top-Down trial recruited 133 immunosuppressant and anti-TNF-naive patients with moderate to severely active Crohn's disease within 4 years of diagnosis." (PMID 38402895, 2024). "Infliximab (IFX), an anti-tumor necrosis factor alpha (anti-TNFα) inhibitor, is used for induction and maintenance therapy in Crohn's disease." (PMID 39618753, 2024). "TNF∆ARE/+ mice, in which TNF-α is constitutively overproduced, exhibit the spontaneous development of Crohn’s disease-like ileitis." (PMID 39327633, 2024). "Treatment with anti-tumour necrosis factor α antibodies [anti-TNF] changes the dysbiotic faecal bacteriome in Crohn’s disease [CD]." (PMID 37527838, 2024). "In the study, bioinformatics and experimental research identified TLR2, TREM1, CXCR1, FPR1, and FPR2 as promising candidates for predicting the anti-TNFα response in patients with Crohn’s disease and especially TLR2 as a core predictor." (PMID 39062093, 2024).